TFRC (transferrin receptor)
Diseases named in the same sentence as TFRC in open-access papers (continued):
Sharing a sentence is not in itself a finding about the gene and the disease.
cancer (continued). "A recent study has shown that Yap is associated with the activation of ferroptosis, Yap can promote an iron environment in cancer cells through stimulating transcription of TEAF-based members of the Transferrin receptor (TFRC) and Acyl-CoA synthetase long chain family 4 (ACSL4)." (PMID 37005430, 2023). "Moreover, Ru can bind to transferrin receptors in order to enter cells, and because cancer cells contain a high transferrin receptor density, Ru accumulates preferentially into tumors." (PMID 37686420, 2023). "Transferrin receptor (TfR) is highly expressed on the surface of cancer cells." (PMID 37919282, 2023). "HFn binds the transferrin receptor 1 (TfR1) that is overexpressed in many cancers." (PMID 36273205, 2022). "The excessive iron load may lead to ferroptosis in cancer patients, membrane transferrin receptor 1 (TFR1) can transport Fe3+ ions into cells, was also recently identified as a biomarker for ferroptosis." (PMID 35688814, 2022). "We analyzed TCGA data related to TFRC expression levels in a variety of cancers." (PMID 35372510, 2022). "A tumor-targeting immunoliposome nanocomplex decorated with an anti-transferrin receptor single-chain antibody fragment (“scL-TMZ”) prepared using this method has been shown to possess an enhanced anti-cancer effect in animal models of GBM when compared to free TMZ." (PMID 35214041, 2022). "Finally, as cancer cells appear to be “addicted to iron” and as the TFRC emerged as a new cancer marker, we tested the expression of the TFRC in human GIST tissues and explored possible correlations with clinicopathological criteria and YAP expression." (PMID 36291834, 2022). "Therefore, manipulating iron metabolisms, such as using iron chelators, transferrin receptor 1 (TFR1) Abs, and cytotoxic ligands conjugated to transferrin, has become a considerable strategy for cancer therapy." (PMID 34962017, 2022). "The induction of ferroptosis is also resistant to chemoradiotherapy in cancer, and the transcriptional coactivator, Yes-associated protein, is activated in drug-resistant cancer cells, thereby enhancing ferroptosis sensitivity by activating two iron-promoting factors, ACSL4 and TFRC." (PMID 36686700, 2022). "The transferrin receptor (TfR) is frequently upregulated in cancer cells, suggesting that iron flux may be increased in cancer cells." (PMID 36338346, 2022). "Therefore, the findings of our current study should be comprehended alongside with the previous studies’ results, as we found that TFRC is involved in the occurrence and development of many cancers." (PMID 35372510, 2022). "TFRC displayed moderate to strong cytoplasmic expression in various cancer tissues." (PMID 35752862, 2022). "Transferrin receptor (TfR) is a well-known target for diagnosis and treatment of cancers." (PMID 34959326, 2021). "Indeed, HFn is internalized in cancer cells upon its specific binding with the Transferrin receptor 1 (TfR1), which is overexpressed in almost all kinds of cancer." (PMID 33562060, 2021). "TFRC is a cell surface receptor that is responsible for transferrin‐mediated iron uptake; thus, TFRC may play a key role in the energy supply of cancer cells." (PMID 33626208, 2021). "Transferrin receptor-targeting dendrimers have demonstrated efficiency in delivering therapeutic genes and drugs to cancer cells and their use has already led to significant improvements in cancer therapies." (PMID 35237758, 2021). "The transferrin receptor is mainly expressed on hepatocytes, myocytes, basal keratinocytes, endocrine pancreas, spermatocytes, and the erythroid precursor and is abnormally expressed in many types of cancer." (PMID 32070033, 2020). "Multiple strategies for anticancer therapies, including utilization of TFRC-mediated cytotoxic drug conjugates and iron chelators, have been designed to disrupt the intracellular iron balance needed to meet the urgent metabolic demand of cancer cells." (PMID 33204330, 2020).
cancer (continued). "The TFRC protein has been explored for cancer therapy drug delivery due to its endocytic abilities." (PMID 32782317, 2020). "Indeed, several targeted nanoparticle formulations are now being tested in clinical trials for cancer treatment, decorated in their surface with antibodies against transferrin receptor, epidermal growth factor receptor, and ephrin type A receptor 2131." (PMID 32848154, 2020). "Since artesunate has been shown to induce ferroptosis in cancer cells, whether TFRC palmitoylation also contributes to its antitumor activity of ferroptosis needs further validation." (PMID 33117818, 2020). "It is known that the activation of Ras-mitogen-activated protein kinase (MEK) signaling can contribute to the sensitivity of cancer cells to ferroptosis, through the abundant presence of iron in cancer resulting from the regulated expression levels of transferrin receptor and ferritin." (PMID 32214052, 2020). "For specific delivery of liposomes or lipoplexes loaded with siRNA molecules into cancer cells, transferrin may be attached to them to facilitate their binding to cancer cells through transferrin receptor (TfR/CD71) and their active entry into the cells." (PMID 31024572, 2019). "In light of the EV-mediated transfer of biological molecules, magnet-conjugated transferrin bound to transferrin receptor-expressed blood exosomes has been shown to preferentially target magnets surrounding cancer cells, followed by the inhibition of cancer development." (PMID 31078138, 2019). "Transferrin receptor (TfR-1) expression, detected only in lysates prepared from carcinoma cells, may contribute to the cancer-selectivity." (PMID 35539052, 2019). "The activation of Ras-mitogen-activated protein kinase (MEK) signaling can attribute to the sensitivity of cancer cells to ferroptosis, resulting from its promoting iron abundance in cancer by governing the expression levels of the transferrin receptor and ferritin." (PMID 30925886, 2019). "This, in addition to the presence of transferrin and transferrin receptor on cancer derived exosomes, supports the hypothesis that TfR1 plays a role in exosome internalization." (PMID 30405884, 2018). "Epidermal growth factor receptor-2 (EGFR-2) and transferrin receptor (TfR) is also useful biomarkers for targeting both cancer cells, and CSCs and delivery of nanoparticles carrying drug molecules specifically to these cells would be an intelligent approach to eradicating them simultaneously." (PMID 28785557, 2017). "Moreover, due to their generally elevated proliferative potential, cancer cells have a greater metabolic demand for iron than normal cells and hence express high levels of transferrin receptor (TfR1) to internalize transferrin-bound circulating iron." (PMID 29247214, 2017). "However, we showed that the anti-TFRC antibody was more effective against cancer cells that expressed high levels of TFRC than against those with low TFRC expression." (PMID 24890018, 2014). "Some studies reported high iron concentration promoted the cancer cell proliferation by overexpressing transferrin receptor that could elevate the level of reactive soluble iron in cells." (PMID 23301003, 2013). "Notably, cancer cells develop abnormally high concentrations of metal ions due to overexpression of the transferrin receptor." (PMID 24454991, 2013). "Because it has been shown that many types of cancer cells exhibit increased surface levels of the transferrin receptor (TfR), attempts have been made to various cytotoxic agents to transferrin, with the goal of targeting that cytotoxic agent to cancer cells through endocytic uptake by the TfR." (PMID 23887041, 2013). "For application of these nanoparticles to cancer, the transferrin receptor (TfR) was selected as a target owing to its significant overexpression on a variety of cancer cell types; indeed, TfR is a well-studied surface protein for targeting of cancer therapeutics." (PMID 22496980, 2012).
cancer (continued). "Taken together, all these observations might suggest to further investigate the usefulness of VEGFA, MET and TFRC as common cancer biomarkers." (PMID 22761861, 2012). "Transferrin receptor (TfR) significantly over-expressed in a variety of cancers cells may be the primary target of GA." (PMID 21777476, 2011). "A covalent conjugate of artemisinin and transferrin (ART-Tf), an iron transport protein in human, is actively taken up by cancer cells through the transferrin receptor (TfR)-mediated endocytosis pathway, and shows significantly higher anti-cancer activity than unconjugated artemisinin." (PMID 20657468, 2010). "Several genes encoding protein products that are important in cancer and have functions related to cell cycle, growth, DNA replication and protein translation (such as CCND1, TOP2A, TOPBP1, TFRC; three members of H4 histone family [HIST1H4C, HIST1H4B, and HIST1H4E]; and EIF4G1)." (PMID 17498291, 2007). "The expression of transferrin receptor (TfR) has been identified in many malignant tumours." (PMID 9192985, 1997). "Another important factor in this study was the fact that the cells were treated at confluence for a relatively long time (48 h), and this condition may contribute to the modulation of the expression of at least FTH1, FTL, and TFRC if compared with cells in active proliferation, such as cancer cells." (PMID 41303636, 2025). "Additionally, the use of small molecules that inhibit TFRC function has been explored as a potential strategy to disrupt iron homeostasis in cancer cells, thereby inducing ferroptosis, a form of regulated cell death characterized by iron-dependent oxidative stress." (PMID 40303995, 2025). "The exploration of TFRC as a target has gained momentum in recent years, with numerous studies investigating its implications in both small molecule drug development and gene therapy applications aimed at enhancing therapeutic efficacy and specificity in cancer treatment." (PMID 40303995, 2025). "Also, transferrin receptor 1, required for iron importation from transferrin into cells via endocytosis, has been identified as a downstream target of the Myc network and is overexpressed in cancer tissue, contributing to higher levels of cellular iron intake." (PMID 38732562, 2024). "Cancer cells with mutant RAS (including KRAS), such as HNSCC cells, are sensitive to the induction of ferroptosis, which may be due to the mutated expression of iron metabolism genes mediated by RAS, such as transferrin receptor TFRC, FTH1 and FTL." (PMID 36600313, 2023). "Therefore, additional functional studies are necessary to clarify whether TFRC is a pro-ferroptosis marker or, perhaps, it is a pan-cancer dependency independently of ferroptosis." (PMID 35912247, 2022). "In addition, we found that TFRC has a high expression level in several cancers, including LGG." (PMID 36483569, 2022). "Therefore, inducing ferroptosis in TFRC-expressed cancers is a potential cancer treatment strategy." (PMID 33117818, 2020). "In addition to cancer, reduced TFRC palmitoylation has been demonstrated to contribute to neurodegeneration accompanied by brain iron accumulation, while the antimalarial agent artesunate can reverse the abnormal TFRC palmitoylation in cultured fibroblasts of neurodegeneration subjects." (PMID 33117818, 2020). "The transferrin receptor (TfR), is located in the cell membrane surface and plays an important role for transporting ferric ion and is an accessible portal for the cancer drug delivery due to the expression level of TfR on cancer cell being high, relative to the normal cell." (PMID 31557852, 2019). "Moreover, treatment with either ferrous iron or transferrin can enhance the cytotoxicity of DHA toward cancer cells, which could be reversed by iron chelator or anti-transferrin receptor antibody." (PMID 31519193, 2019). "Additionally, we assessed the use of transferrin receptor to identify other cancer cell types." (PMID 26111884, 2015).
cancer (continued). "In various cancer and oxidative stress models, activation of the RAS–JNK/p38 signaling cascade upregulates transferrin receptor 1 (TfR1), enhancing iron uptake and making cells more susceptible to ferroptosis under oxidative conditions." (PMID 41383846, 2025). "Most of these proteins are recognized as potential prognostic biomarkers in liver (TFRC and GPLD1), renal (IGHG1, PRCP, SAA1/2, and IL1RAP) and digestive (PRSS3) cancers in the Human Protein Atlas database." (PMID 41155404, 2025). "This is because the ferritin heavy (H)-chain has a high attraction toward human transferrin receptor-1 (CD71), that is upregulated in cancer cells." (PMID 36866455, 2023). "Transferrin Receptor (TfR, TfR1, TFRC) is a membrane protein commonly overexpressed by cancer cells, making it an appealing target for anti-cancer biomaterials such as molecular probes or nanoparticles." (PMID 38117806, 2023). "Further, endocytosis is involved in activation of certain cancer receptors such as Epidermal growth factor receptor (EGFR), Transferrin receptor (TfR), and Notch receptor." (PMID 36769293, 2023). "In comparison to cancer cells, CSCs showed lower expression of ferroportin 1 (FPN1) and hephaestin, which regulate iron outflow, and higher levels of transferrin receptor (TfR), which controls the iron influx through TF/2Fe3+." (PMID 38067114, 2023). "A good example is the TEPP bifunctional aptamer that from one end targets transferrin receptor (TfR) located on BBB ECs, and from the other end targets epithelial cell adhesion molecule (EpCAM) located on cancer cells within the brain." (PMID 37686652, 2023). "Thus, the role of TFRC in cancer progression remains unclear." (PMID 37644594, 2023). "TFRC (transferrin receptor) promoted the proliferation and metastasis of cancer cells by upregulating the expression of AXIN2, which accelerated the development of cancer." (PMID 35807355, 2022). "To better understand the cellular functions of these prioritized RBPs (TFRC, KPNB1, PUF60, NSF, and SF3A3) in cancer, we next interrogated the HumanNet v2." (PMID 35453681, 2022). "The quantitative analysis of the gene expression involves five reference genes (ACTB, TFRC, GAPDH, GUSB, and RPLP0) and 16 cancer-related genes." (PMID 36042999, 2022). "These putative BC progressor RBPs (PUF60, TFRC, KPNB1, NSF, and SF3A3) were integrated into a disease gene network to shed light on their molecular and cellular functions in cancer." (PMID 35453681, 2022). "Researchers are searching for the dynamic biomarkers applied in non-invasive methods that can indicate the cancer characteristics, such as HE4, transferrin receptor 1 (TFR1), and cancer antigen 125 (CA-125)." (PMID 34861867, 2021). "LF can bind to transferrin receptors (TFR) and LF membrane internalization receptors (LFR) that are characteristic of cancer cells." (PMID 33921992, 2021). "KEGG analysis identified adhesion, hematopoiesis and cancer-related proteoglycans as affected pathways (e.g. metformin: CD9, CTSL, IL5, HGF; insulin: EGF, EZR, PLCG2, TFRC)." (PMID 33690729, 2021). "The most stable expressed gene in MM cancer tissues was ACTB, with a lower average between mean SD and mean Ct (1.17 for ACTB; 1.22 for HPRT1; 1.62 for TFRC), while in CSCC cancer tissues it was TFRC (1.00 for TFRC; 1.13 for HPRT1; 1.45 for ACTB)." (PMID 34940125, 2021). "As a result, the unmasked ferritin was internalized via its natural transferrin receptor-1 (TfR-1 or CD71), which is overexpressed on cancer cells." (PMID 31527483, 2019). "However, it is speculated that cancer cells require more iron than normal cells to sustain their abnormally rapid growth rate, and reduction in the intracellular iron concentration by preventing TFRC-mediated cellular iron uptake may induce growth inhibition and cell death in cancer cells." (PMID 24890018, 2014).
cancer (continued). "Elevated c-Myc activity, a driver of transformation in many cancers, tends to increase the LIP by promoting transcription of the transferrin receptor and IRP2, while suppressing transcription of the ferritin heavy chain (FHC)." (PMID 25279352, 2014). "In summary, we demonstrate that PTPN2 exerts cancer‐promoting effects by TFRC‐mediated mitophagy, a process that is independent of ferroptosis." (PMID 40734623, 2025). "The targeted cancer therapies for HCC usually employ receptors like asialoglycoprotein receptor (ASGPR), glycyrrhetinic acid receptor, transferrin receptor, somatostatin receptor, folate receptor, retinoic acid receptors or epidermal growth factor receptor etc. to deliver drugs to liver tumors." (PMID 38990437, 2025). "Furthermore, PRDM1 and IRF, which exhibit higher activity in CD8+ T cells, induce ferroptosis in cancer cells by inhibiting the transcription of GPX4 and driving the expression of transferrin receptor, respectively, thereby improving the TME." (PMID 40454580, 2025). "Studies have reported that pairing the Met receptor aptamer with a cancer cell biomarker, CD71 or Transferrin receptor (TfR), using a bispecific aptamer interferes with the interaction between the Met receptor and hepatocyte growth factor (HGF), thereby inhibiting cancer cell metastasis." (PMID 39407665, 2024). "In conclusion, we reported a novel mechanism of METTL3 desensitization to ferroptosis via regulating TFRC, and an appropriate reduction of METTL3 might sensitize cancer cells to ferroptosis-based therapy." (PMID 38221933, 2024). "Notably, overexpression of LASS2 reversed the changes in these cancer cells, such as changes in metastasis and ferroptosis-related protein levels (EMT, TFRC, GPX4, FTH1 and FTL1), induced by Fer-1 or erastin." (PMID 38419028, 2024). "Moreover, cancer cells exhibiting overexpression of the transferrin receptor, a cargo molecule associated with CME, demonstrate enhanced uptake of exosomes, indicating that alterations in receptor expression levels may modulate the efficiency of exosome internalization in cancer cells." (PMID 38542535, 2024). "Transferrin (TF) and transferrin receptor (TFR) bind to form a complex that is involved in intracellular iron transport and is the main pathway for iron uptake by cancer cells, which was found to be essential for the induction of cellular ferroptosis by glutamine depletion assays." (PMID 37818101, 2023). "Our research also found TFRC knockdown by siRNA could significantly inhibit the growth, migration, and invasion of NPC cells, which is consistent with previous studies on most cancers." (PMID 37644594, 2023). "Protein TFRC, the protein most abundantly expressed in OSCC cancer tissues, and identified in all cancer cell lines secretomes, is an especially promising candidate non-invasive biomarker that was previously not reported and merits further evaluation for its potential for the detection of OSCC." (PMID 35130834, 2022). "On the other hand, iron is an essential nutrient for cancer cell proliferation, and iron (Fe(III))-loaded transferrin is transported into cells by binding to the transferrin receptor on the cell surface and the induction of clathrin-mediated transferrin endocytosis." (PMID 26036864, 2015). "Therefore, this phenomenon can introduce cerium as a candidate to inhibit cancer cell proliferation and the effectiveness of cerium in the presence of transferrin showed that this element may have a similar mechanism of endocytosis mediated by transferrin receptor." (PMID 26664465, 2015). "HIF-1 activity is constitutively active in many aggressive cancers, and is typically elevated in hypoxic tumor regions; since HIF-1 promotes transcription of the gene coding for the transferrin receptor, it would be expected to increase the intracellular iron pool." (PMID 25279352, 2014). "The mechanism behind the selective cancer cell killing ability of the anti-TFRC antibody has not yet been elucidated." (PMID 24890018, 2014).